CELF3 (CUGBP Elav-like family member 3)
Description:
RNA-binding protein involved in the regulation of pre-mRNA alternative splicing. Mediates exon inclusion and/or exclusion in pre-mRNA that are subject to tissue-specific and developmentally regulated alternative splicing. Specifically activates exon 5 inclusion of cardiac isoforms of TNNT2 during heart remodeling at the juvenile to adult transition. Activates the splicing of MAPT/Tau exon 10. Binds to muscle-specific splicing enhancer (MSE) intronic sites flanking the alternative exon 5 of TNNT2 pre-mRNA.
Synonyms: ETR-1; BRUNOL1; CAGH4; ERDA4; TNRC4; MGC57297
Tractability: PROTAC: ubiquitination databases record sites on it; its protein half-life has been measured.
Gene: Protein-coding gene on chromosome 1 (151,700,058 to 151,716,803, reverse strand). Ensembl gene ENSG00000159409.
Subcellular location: Nucleus; Cytoplasm
Subcellular location (Human Protein Atlas): Nucleoplasm
Gene Ontology:
Molecular function: RNA binding; pre-mRNA binding; 7SK snRNA binding; nucleic acid binding
Biological process: positive regulation of mRNA splicing, via spliceosome; regulation of alternative mRNA splicing, via spliceosome; RNA splicing; mRNA splice site recognition; gene expression
Cellular component: cytoplasm; nucleus; ribonucleoprotein complex; nuclear body
Genetic constraint (gnomAD): Loss-of-function variants: 26 observed, 54.49 expected, observed/expected ratio (o/e) 0.48, 90% interval 0.35 to 0.66. The upper end of that interval is the gene's LOEUF score, 0.66, which puts it in group 2 of 6, group 1 being the genes least tolerant of losing a copy. Missense variants: 387 observed, 598.48 expected, observed/expected ratio (o/e) 0.65, 90% interval 0.59 to 0.7. Synonymous variants: 245 observed, 235.96 expected, observed/expected ratio (o/e) 1.04, 90% interval 0.94 to 1.15.
Homologues: Orthologues: rat Celf3 (99% identical), dog CELF3 (99% identical), mouse Celf3 (99% identical), guinea pig CELF3 (99% identical), chimpanzee CELF3 (97% identical), pig CELF3 (91% identical), tropical clawed frog celf3 (87% identical), rabbit CELF3 (82% identical), macaque CELF3 (80% identical), zebrafish celf3a (80% identical), zebrafish celf3b (77% identical), Drosophila melanogaster bru2 (42% identical), and 5 more. Paralogues in human: CELF6 (69% identical), CELF4 (68% identical), CELF5 (66% identical), CELF2 (49% identical), CELF1 (48% identical), RBM28 (23% identical).
Diseases named in the same sentence as CELF3 in open-access papers:
CELF3 is named in the same sentence as 7 diseases in open-access papers, as found by Europe PMC text mining. Sharing a sentence is not in itself a finding about the gene and the disease. The quoted sentences say what the papers report.
cardiomyopathies (1 paper, 2015). "Consequently, other RNA-binding proteins such as CELF-3, CELF-5, RBM24, RBM25 and LUC7L3 have been linked to the development of cardiomyopathies." (PMID 26116573, 2015).
glioma (1 paper, 2020). A benign or malignant brain and spinal cord tumor that arises from glial cells (astrocytes, oligodendrocytes, ependymal cells). "In addition, the expression levels of four of these genes (ATCAY, CELF3, ELAVL3 and UGT8) were highest in normal brain tissues, and negatively correlated with glioma grades." (PMID 32091665, 2020).
neuroblastoma (1 paper, 2014). Neuroblastoma (NB) is the most common solid, extracranial childhood tumor. "In the neuroblastoma cell line Neuro2A, Celf3 formed novel nuclear bodies (named CS bodies) that colocalized with SF1, another Gomafu-binding protein." (PMID 25145264, 2014). "Interestingly, Celf3 formed novel nuclear bodies (CS bodies) in the neuroblastoma cell line Neuro2A that colocalized with SF1, another Gomafu-interacting protein." (PMID 25145264, 2014).
schizophrenia (1 paper, 2019). A major psychotic disorder characterized by abnormalities in the perception or expression of reality. "We show that ZNF804A is a nuclear protein that interacts with neuronal RNA splicing factors and RNA-binding proteins including RBFOX1, which is also associated with schizophrenia, CELF3/4, components of the ubiquitin-proteasome system and the ZNF804A paralog, GPATCH8." (PMID 30597088, 2019).
cancer (1 paper, 2022). A tumor composed of atypical neoplastic, often pleomorphic cells that invade other tissues. "As for the other 2 mRNA, VPS13D and CELF3, some multi-omics or pathways based analysis indicated the their roles as potential drug target or biomarker for metastasis, but more experimental evidences are needed to further confirm their molecular roles in cancer biology." (PMID 35751033, 2022).
CELF3 also shares sentences with these, for which no sentence is quoted: benign neoplasm (1 paper); fibrosis (1).